RNU1-86P (RNA, U1 small nuclear 86, pseudogene)
Gene: Small nuclear RNA gene on chromosome Y (23,946,618 to 23,946,771, reverse strand). Ensembl gene ENSG00000251917.
Homologues: Orthologues: macaque U1 (78% identical). Paralogues in human: RNU1-107P (100% identical), RNU1-41P (81% identical), RNU1-48P (81% identical), RNU1-128P (80% identical), RNU1-95P (80% identical), RNU1-40P (79% identical), RNU1-97P (79% identical), RNU1-1 (78% identical), RNU1-2 (78% identical), RNU1-27P (78% identical), RNU1-28P (78% identical), RNU1-3 (78% identical), and 134 more.